PAK4 (p21 (RAC1) activated kinase 4)
Diseases named in the same sentence as PAK4 in open-access papers (continued):
Sharing a sentence is not in itself a finding about the gene and the disease.
cancer (continued). "Pak4 has essential roles in embryonic development, but in adults high levels of Pak4 are frequently associated with cancer." (PMID 23326684, 2012). "Among the group B Paks, Pak4 is most closely linked to cancer, and it is overexpressed in many types of tumors and cancer cells." (PMID 23326684, 2012). "Furthermore, in the in vivo model, a higher expression of PAK4 was associated with the increased peritumoral infiltration of immune cells related to the immune evasion of cancer cells, FOXP3-, and PD1-positive cells." (PMID 39273017, 2024). "When considering the divergent roles of PAK4 and PHF8 in cancer progression, there might be a direct or indirect association between PAK4 and PHF8." (PMID 36980457, 2023). "The overexpression of p21-activated kinase 4 (PAK4) is associated with a variety of cancers." (PMID 36615619, 2023). "PAK4 is one of the PAKs most closely associated with cancer." (PMID 36615619, 2023). "In addition to the classical signaling pathways, PAK4-related axes were also reported associated with cancer." (PMID 36105226, 2022). "PAK1 and PAK4 proteins are associated with cancer tumorigenesis." (PMID 31658701, 2019). "PAK4 is associated with a poor prognosis in various cancers and promotes migration and invasion." (PMID 30177834, 2019). "Besides this, a functional association of PAK4 with tumor phenotypes has also been established in some cancers." (PMID 25238288, 2014). "Besides, there is a novel association between Gab1 and PAK4, and PAK4 is a key intergrator of cancer cell migration and invasive growth downstream from the Met receptor." (PMID 27919028, 2014). "In order for Pak4 to be a fully effective drug target, however, better understanding of the mechanisms by which it causes cancer may be needed." (PMID 23326684, 2012). "Alterations in cell polarity can be important in cancer, and the role for Pak4 in polarity could help explain how Pak4 could cause cancer." (PMID 23326684, 2012). "In addition, PAK4 lies downstream of EGFR in the ERBB signaling pathway; hence, the nine FDA-approved cancer drugs targeting EGFR should be assessed to see if they ameliorate the effects of PAK4 mutations and could be used to treat HGSOC patients." (PMID 27788148, 2016). "The PAK family, divided into group I (PAK1–3) and group II (PAK4–6), regulates cancer cell migration, invasion, and endothelial permeability through modulation of cytoskeletal dynamics and contractility." (PMID 41228228, 2025). "PAK4 is overexpressed in various types of cancers and plays an important role in tumor invasion and metastasis." (PMID 40180890, 2025). "We also assessed the biological effects of the inhibition of autophagy on PAK4 KO cancer cells, especially on the expression of cell surface immune markers such as MHC I." (PMID 39941877, 2025). "We found that PAK1 knockout reduced tumour growth and new blood vessel formation while improving vessel normalisation, whereas PAK4 knockout increased vessel diameter and sensitised cancer cells to chemotherapy." (PMID 41228228, 2025). "We expect that more effective PAK4 inhibitors will be developed and applied in clinical cancer treatment in the future." (PMID 40332759, 2025). "Given the changes in BCL2, we also evaluated the effect of CQ on WT and PAK4 KO cancer cell apoptosis." (PMID 39941877, 2025). "This study highlights the previously unrecognized role of RBCs in promoting metastatic behavior in cancer cells and suggests potential therapeutic targets, such as PAK4, to counteract these effects." (PMID 40301999, 2025). "PAK1 is implicated in cytoskeletal remodelling and endothelial permeability, whereas PAK4 influences cancer cell survival, stemness, and therapy resistance." (PMID 41228228, 2025). "Beyond its established role in cancer, our previous studies have revealed several novel physiological functions of PAK4." (PMID 41328324, 2025).
cancer (continued). "This indicates that PAK4 inhibition is likely to have a cell-specific effect on PDL1 expression due to cancer cell heterogeneity." (PMID 39941877, 2025). "As autophagy is recognized for its cytoprotective effect on cancer cell survival, we assessed the combined effect of CQ and PAK4 KO on MiaPaCa-2 and PANC-1 cell growth." (PMID 39941877, 2025). "P21-activated kinase 4 (PAK4) plays a crucial role in the proliferation and metastasis of various cancers." (PMID 39852144, 2025). "PAK4 plays a multifaceted role in cancer progression by regulating cytoskeletal dynamics, promoting cancer cell survival, enhancing stemness, and modulating the tumour immune microenvironment through suppression of T-cell-mediated responses." (PMID 40943273, 2025). "Consistently, the prognostic significance of the expression of PAK4 and PD-L1 has been reported in various human cancers." (PMID 39273017, 2024). "In patient tumor samples, PAK4’s inhibition is positively correlated with immune-hot tumor microenvironment in 22 cancer types." (PMID 38609378, 2024). "The expression of PAK4 was increased in various human cancers and related to a poor prognosis for cancer patients, so was proposed as a potential therapy target for cancer patients, including those with sarcomas." (PMID 39273017, 2024). "We found that UCHL1 and SNRNP200 are significantly upregulated, and PAK4 is downregulated in high-grade CCRCC, and all are involved in critical cellular pathways linked to cancer progression and poor clinical outcomes." (PMID 39199615, 2024). "P21 activated kinase 4 (PAK4) plays a critical role in various signaling pathways in cancer, including the Wnt/β-catenin, RAS-ERK, and androgen/estrogen receptor pathways." (PMID 39272943, 2024). "Pak4 positive rate was statistically significant among different cancer histology types (P = 0.037)." (PMID 38807162, 2024). "In particular, P21-activated kinase 4 (PAK4) is involved in the progression of various human cancers by affecting cellular proliferation, apoptosis, invasiveness, cancer metabolism, and immune regulation." (PMID 39273017, 2024). "Although KPT-9274 was previously shown to inhibit both PAK4 and NAMPT, we had assumed that most PAK4 inhibitors block cancer cell growth primarily due to the inhibition of PAK4." (PMID 39337621, 2024). "Our data suggest that RAC1 expression is upregulated in PTX‐resistant cancer cells, thereby promoting signaling via the PAK4/MAPK pathway and inhibiting chemotherapy‐induced pyroptosis." (PMID 39224538, 2024). "Understanding how PAK4 inhibitors operate is important, as they have been shown to reduce the growth of several types of cancer cells, highlighting their potential for cancer therapy." (PMID 39337621, 2024). "In this study, we have determined the effect of dual inhibition of PAK1 and PAK4 in PDA progression using knockout (KO) cancer cell lines." (PMID 38797819, 2024). "In particular, PAK4 has garnered attention for its tendency to be overexpressed in numerous human cancer cell lines and tumors." (PMID 38649421, 2024). "The growth of cancers generated by cisplatin-resistant cells (A549-res cells) was significantly suppressed in the PAK4 knockdown group." (PMID 38238316, 2024). "It should be noted that these results cannot be used to determine the efficiency of targeting PAK4 in patients with PAK4-overexpressing cancer." (PMID 38238316, 2024). "One particularly intriguing among these approaches is p21 activated kinase 4 (PAK4), widely expressed in different cancers, and it holds significant promise as a potential chemotherapeutic target." (PMID 38890401, 2024). "PAK4 is overexpressed across different cancer types and has been proposed as a biomarker for cancer." (PMID 39272943, 2024). "In well-differentiated carcinoma cells, the immunostaining of PAK4 was slightly more intense than that in the normal epithelium and was mainly observed in the cytoplasm in the carcinoma areas." (PMID 38890401, 2024).
cancer (continued). "Inhibiting PAK4 or STAT3 reduces stem cell-like characteristics in cancer cells, offering potential therapeutic options." (PMID 38067120, 2023). "Exosome-mediated RNAi intra-tumorally verified P21-activated kinase 4 (PAK4) as a therapeutic target in an in vivo PC cancer mouse model." (PMID 37405480, 2023). "It has been shown that p21-activated kinase 4 (PAK4), a serine/threonine protein kinase, was critical for cancer progression." (PMID 38028153, 2023). "Many scientific studies confirmed that PAK4 is overexpressed in a variety of human cancers, such as breast, pancreatic, gallbladder, gastric, hepatocellular, and esophageal cancers." (PMID 36615619, 2023). "Inhibition of PAK4 with specific inhibitors has been shown to inhibit the proliferation of cancer cells and induced restoration of sensitivity to anticancer agents." (PMID 36980457, 2023). "The promoting role of PAK4 in glucose intake and lipid biosynthesis in cancer cells has also been reported." (PMID 36672500, 2023). "It is worth mentioning that PAK4 is often overexpressed in cancer cells and highly induced during oxidative stress." (PMID 37591884, 2023). "PAK4 expression was higher in cancer tissue and a higher expression was related to a more aggressive phenotype and a poorer prognosis in various human cancers." (PMID 36980457, 2023). "Hyperactivation of PAKs also supports cell survival over cell death, and the targeted depletion of PAK1, PAK2, or PAK4 in human cancer cell lines has been shown to compromise fitness and ability to survive in a variety of cancer types." (PMID 36830998, 2023). "The importance of PAK4 and PHF8 in cancer progression and as therapeutic targets has been emphasized in various human cancers, and the inhibition of PAK4 and PHF8 is under evaluation in cancer therapy." (PMID 36980457, 2023). "PAK4-regulated endothelial cell plasticity contributes to the modification of the vascular microenvironment and thus the efficacy of cancer therapy." (PMID 38067120, 2023). "The mechanism of PAK4 in cancer progression has been suggested by its role in regulating various aspects of cancer cell behavior, such as proliferation, invasiveness, angiogenesis, metabolic reprogramming, and immune evasion." (PMID 36980457, 2023). "The most extensively studied members among the PAK proteins are PAK1 and PAK4, which have been found to be overexpressed in many types of cancers." (PMID 38067120, 2023). "Other cancers: PAK4 on activation (phosphorylation at Ser474) is well correlated with prostate cancer progression." (PMID 36830998, 2023). "Recent studies revealed that inhibition of PAK4 sensitizes immunotherapy which has been extensively exploited as a new strategy to treat cancer." (PMID 36105226, 2022). "Taken together, PAK4 is widely distributed in normal human tissues with low levels, and overexpressed in tumors, a clear indication of correlation between PAK4 and cancer." (PMID 36105226, 2022). "A large number of studies have shown that PAK4 is intimately involved in proliferation, migration, invasion, drug resistance and immune escape of cancer cells." (PMID 36105226, 2022). "Previous studies have reported that Pak4 expression silencing induces a spherical cell morphology via actin dynamics in cancer cell lines." (PMID 36301793, 2022). "The inhibition of PAK4 improves the results that are obtained by the application of chimeric antigen receptor-T cell immunotherapy (CAR-T) against cancer." (PMID 36230657, 2022). "Recent studies revealed that PAK4 plays an important role in promotion of immune escape of cancer cells, warranting for PAK4 as a promising target for immunotherapy." (PMID 36105226, 2022). "P21 activated kinase 4 (PAK4) is a member of Group 2 of the p21 activated kinases, which are downstream effectors of CdC42 and Rac1 and participate in biological behaviors of cancer." (PMID 35842733, 2022).
cancer (continued). "P21-activated kinase 4 (PAK4) has been demonstrated to function as an oncogenic protein in various cancers, including HCC." (PMID 35629368, 2022). "PAK4 forms a protein complex with NAMPT, which is crucial for mitochondrial function and has been implicated in cancer metabolism and stemness." (PMID 35241781, 2022). "PAK4 overexpression correlates with various cancers, including breast cancer, ovarian cancer, pancreatic cancer, prostate cancer, gastric cancer, and gliomas." (PMID 35328758, 2022). "It has been reported that LINC01224 is highly expressed in epithelial ovarian cancer and can promote the development of the cancer through miR-485-5p–mediated PAK4." (PMID 35433686, 2022). "Inka1 was reported to serve as a Pak4 inhibitor in cancer cell lines; however, the physiological function of Inka2 is unclear." (PMID 36301793, 2022). "Inhibition of PAK4 was found to attenuate cancer cell migration and invasion, and suppress growth of diverse tumors in vivo." (PMID 36105226, 2022). "Pharmacological inhibition of PAK4 attenuates proliferation, migration, and invasion of cancer cells." (PMID 36105226, 2022). "The functions of PAK4 in diseases have principally been investigated in cancers, and overexpression of it contributes to tumorigenesis." (PMID 33615605, 2021). "This role is often altered in cancer cells, as a consequence of the activation of other pathways peculiar of transformed cells, such as the O-glycosylation (O-GlcNAc) pathway or the p21 Activated Kinase 4 (PAK4)-dependent activity." (PMID 34065551, 2021). "PAK4, for example, activates the Wnt signaling pathway, which is a commonly dysregulated signaling pathway in cancers." (PMID 36594908, 2021). "PAK1 and PAK4, for instance, are of particular interest in cancer biology due to their involvement in tumor formation and upregulation in various cancer types." (PMID 36594908, 2021). "One prior study indicated that PAK4 expression levels are negatively correlated to immune cell infiltration in numerous human cancer types." (PMID 36594908, 2021). "PRP4 kinase is important for regulation cell growth and survival of cancer, and it is reported to phosphorylate Ser104 on PAK4." (PMID 34009729, 2021). "PAK4 inhibition by RNAi or small molecule drugs has been shown to dramatically decrease cancer progression, migration, and tumor size in several malignancies." (PMID 35008323, 2021). "The Cdc42 kinase effectors PAK1, PAK2, PAK4, MRCKα, MRCKβ and ACK have all been directly targeted, consistent with cancer mutational data indicating that these proteins show the highest incidence of alterations amongst the Cdc42 effectors." (PMID 34100887, 2021). "Dual inhibition of NAMPT and PAK4 signalling has therapeutic application in a number of cancers due to synergism." (PMID 34100887, 2021). "The chromosomal region coding for PAK4, 19q13.2, is amplified in many aggressive cancers and therefore overexpressed in cancer cell lines, while it is undetectable in normal cells." (PMID 35008323, 2021). "P21-activated kinase 4 (PAK4), a member of serine/threonine kinases family is over-expressed in numerous cancer tumors and is associated with oncogenic cell proliferation, migration and invasion." (PMID 33051544, 2020). "A recent study confirmed that miR-145 is involved in the inhibition of cancer cell migration and invasion through the p21-activated kinase 4 (PAK4)-dependent pathway." (PMID 33291485, 2020). "Amongst the PAK family members, PAK1 and PAK4 are the most studied in human cancers, due to their central roles in many oncogenic signaling pathways, and they have emerged as potential therapeutic targets in cancer." (PMID 32863957, 2020). "PAK4 is the earliest discovered and the most representative member in group II PAKs which are mainly reported in mitotic cancer cell research." (PMID 31595158, 2019). "Taken together, this shows that inhibition of PAK4 triggers a senescence-like response in cancer cells of different histological origins." (PMID 31399573, 2019).
cancer (continued). "Because of this strategic role, PAKs, particularly PAK1 and PAK4, have emerged as attractive targets in the field of cancer therapy." (PMID 30755582, 2019). "Accumulating data show that PAK1, PAK3, and PAK4 regulate cell proliferation, motility, and angiogenesis in several types of cancer cells." (PMID 31658701, 2019). "PAK4 plays a pivotal role in cancer progression by accelerating the epithelial–mesenchymal transition, invasion, and metastasis." (PMID 30755582, 2019). "In general, the PAK4 localization is mainly in the cytoplasm and perinucleus, and PAK4 plays crucial roles in a wide range of cellular processes, including promoting cancer cell invasion and migration." (PMID 30177834, 2019). "Based on this evidence, PAK4 is a key regulator of the Wnt/β-catenin signaling pathway and thereby contributes to cancer progression." (PMID 30755582, 2019). "We next examined if PAK4 depletion induced senescence hallmarks in a diverse collection of cancer cells using several in vitro, in vivo, and ex vivo models." (PMID 31399573, 2019). "Based on accumulating evidence, PAK4 represents an alternative target in mutant K-Ras-driven cancers." (PMID 30755582, 2019). "We then examined if the induction of growth arrest upon PAK4 knockdown in cancer cells functionally involved RELB." (PMID 31399573, 2019). "Following successful transfection of pre-miR-199a-3p, protein levels of PAK4 were markedly decreased in all three cancer cell lines." (PMID 29983868, 2018). "Levels of PAK4 mRNA are markedly elevated in all three cancer cell lines compared to hESO cells as measured by both q-PCR and dd-PCR." (PMID 29983868, 2018). "PAK4 regulates many cellular functions related to cancer progression, including cell proliferation and survival as well as cell morphology, adhesion and migration, which are dependent on the actin cytoskeleton." (PMID 29100370, 2017). "Among them, PAK4 is a Cdc42 effector that possesses critical functions in embryonic, neuronal and vascular development, immune defense and cancer." (PMID 29100370, 2017). "PAK4 is highly expressed throughout development as well as in several cancer forms and it is ubiquitously expressed at low levels in many adult tissues." (PMID 28765528, 2017). "PAK4, one target of miR‐145 16, has been found to be up‐regulated in many cancers and considered as an important oncogene that promotes migration." (PMID 28440035, 2017). "PAK4 is overexpressed and genetically amplified in cancer cell lines as well as in cancer patients, including in lung, pancreas, ovary, prostate, breast and gastric cancer, leukemia, oral squamous-cell carcinoma and melanoma." (PMID 29100370, 2017). "The p21-activated kinase 4 (PAK4) is overexpressed in different cancers and promotes proliferation of cancer cells." (PMID 28542136, 2017). "PAK4 is able to promote cancer cell invasion through modulation of the actin cytoskeleton and microtubules." (PMID 28205613, 2017). "On the other hand, to clarify the underlying molecular mechanism of inhibitory effect on invasion of GL-1196, we investigated its impact on the PAK4/LIMK1/cofilin signaling pathway that was reported to be essential for cancer cell migration and invasion." (PMID 27077843, 2016). "As the most extensively and profoundly studied member among the group II PAKs, PAK4 was considered as a key regulator of the signaling network in cancer cells." (PMID 27077843, 2016). "PAK4 is an important oncogene in many cancers, and many of its functions are dependent on PAK4 kinase activity." (PMID 25975262, 2015). "PAK4 is upregulated in many cancers and is an important oncogene that promotes proliferation and migration, and suppresses apoptosis." (PMID 25975262, 2015).